FGD1 (FYVE, RhoGEF and PH domain containing 1)
Diseases named in the same sentence as FGD1 in open-access papers (continued):
Sharing a sentence is not in itself a finding about the gene and the disease.
osteosarcoma (continued). "Finally, we showed that FGD1 was capable of regulating the tumor immune response via the PTEN/PD-L1 axis in osteosarcoma." (PMID 32194840, 2020). "Collectively, FGD1 might be a potential target for improving the survival rate of patients with osteosarcoma." (PMID 32194840, 2020). "Furthermore, our data demonstrated that PTEN knockdown diminishes the growth-inhibitory effect and rescues the down-regulated genes, such as IL-6, PDGF8, CXCL1 and CXCL817, 18, after silencing FGD1 in osteosarcoma tumor cells." (PMID 32194840, 2020). "Silencing FGD1 improved the anti-PD-1 immunotherapy effect on osteosarcoma in mice." (PMID 32194840, 2020). "Taken together, our data indicate that FGD1 promotes the expression of PD-L1 in osteosarcoma." (PMID 32194840, 2020). "Given that FGD1 might be a prognostic biomarker of osteosarcoma, understanding the role of FGD1 in osteosarcoma tumor cells could verify its oncogenic property." (PMID 32194840, 2020). "Our results revealed that FGD1 was markedly overexpressed and might be a prognostic biomarker in osteosarcoma patient specimens." (PMID 32194840, 2020). "Similarly, the protein expression of FGD1 in osteosarcoma tissues was higher than that in the adjacent normal tissues after Western blot analysis or immunohistochemistry (IHC) staining of patient samples, which is consistent with the mRNA levels." (PMID 32194840, 2020). "Similarly, treatment with PI3K inhibitors suppressed the protein and mRNA levels of PD-L1 and diminished the decreasing/increasing PD-L1 expression effect produced by FGD1 repression/overexpression in osteosarcoma tumor cells, respectively." (PMID 32194840, 2020). "In contrast, PD-L1 was increased after ectopic expression of FGD1 in osteosarcoma tumor cells." (PMID 32194840, 2020). "Finally, we demonstrated that FGD1 could regulate osteosarcoma immune response through PTEN/PD-L1 axis." (PMID 32194840, 2020). "Next, we sought to find whether FGD1 modulated the immune response via PD-L1 in osteosarcoma." (PMID 32194840, 2020). "Moreover, we found that FGD1 silencing or overexpression-induced decrease or increase in the phosphorylation levels of AKT could be attenuated by knockdown of PTEN in osteosarcoma tumor cells." (PMID 32194840, 2020). "Therefore, targeting FGD1 might provide a direction in enhancing the anti-PD-1 based immunotherapeutic efficacy in the treatment of osteosarcoma in future experimental and clinical trials." (PMID 32194840, 2020). "Thus, our data indicated a novel biological effect of FGD1 in the tumorigenesis of osteosarcoma." (PMID 32194840, 2020). "Given that the N-terminal region of PTEN is essential for controlling the cytoplasmic localization and activity of PTEN 15, 16 and that PTEN and FGD1 were mutually exclusively in sarcoma patient samples, we wondered whether FGD1 inhibits the function of PTEN in osteosarcoma cells." (PMID 32194840, 2020). "However, the pathological impact of FGD1 in bone tumor, such as osteosarcoma, is still unclear." (PMID 32194840, 2020). "Thus, FGD1 might be a potential target for improving the survival rate of osteosarcomas." (PMID 32194840, 2020). "Therefore, we aimed to explore whether FGD1 modulates PD-L1 expression in osteosarcoma tumor cells." (PMID 32194840, 2020). "Thus, FGD1 might be a novel candidate for osteosarcoma therapy." (PMID 32194840, 2020). "Therefore, our results identified FGD1 as a negative regulator of PTEN, which enhances our current understanding of the biology of osteosarcoma." (PMID 32194840, 2020). "Moreover, FGD1 interacted with PTEN to inhibit its phosphatase activity and re-activated PI3K/AKT/ NF-κB pathway in osteosarcoma tumor cells." (PMID 32194840, 2020). "Notably, FGD1 increased PD-L1 expression in a PTEN dependent manner and modulated the sensitivity of immune checkpoint-based immunotherapy in osteosarcoma." (PMID 32194840, 2020).
osteosarcoma (continued). "Since we identified that FGD1 positively regulated the activation of the PI3K/AKT signaling pathway in osteosarcoma cells, the specific mechanism was still not explicit." (PMID 32194840, 2020). "Interestingly, we found that FGD1 could bind with PTEN to inhibit the activity of PTEN and activate PI3K/AKT/NK-kB signaling in osteosarcoma cells." (PMID 32194840, 2020).
mental retardation (3 papers, 2014 to 2022). "Aside from the FGD1 gene, 4 of the 11 corresponding SNPs sites were associated with intellectual disability." (PMID 35911831, 2022).
autism (2 papers, 2018 to 2021). Persistent deficits in social interaction and communication and interaction as well as a markedly restricted repertoire of activity and interest as well as repetitive patterns of behavior. "FGD6 is an important paralog of the FGD1 gene which is associated with syndromic autism, where some patients are affected with a particular syndrome that presents as autism." (PMID 29888248, 2018).
thyroid cancer (2 papers, 2013 to 2022). "The present study reports for the first time the mutational status of the GNA11, MMP27, FGD1, TRRAP and GRM3 genes in thyroid cancer." (PMID 24137342, 2013). "No FGD1 mutations were identified in 12 thyroid cancer cell lines." (PMID 24137342, 2013). "We previously revealed that FGD1 was normally maintained, hypomethylated and overexpressed by BRAF (V600E) in thyroid cancer cells and in turn observed that it was hyper-methylated after ShRNA-mediated knockdown of BRAF (V600E) in thyroid cancer cell lines." (PMID 24137342, 2013). "We previously demonstrated that FGD1 was normally maintained, hypomethylated and overexpressed by BRAF (V600E) in thyroid cancer cells." (PMID 24137342, 2013). "The mutation status in the GNA11, MMP27, FGD1, TRRAP and GRM3 genes has not been studied in thyroid cancer." (PMID 24137342, 2013). "In conclusion, the present findings suggested that genetic alterations in the GNA11, MMP27, FGD1, TRRAP and GRM3 genes may not be significant in the tumorigenesis of thyroid cancer." (PMID 24137342, 2013).
AIDS (1 paper, 2013). A syndrome resulting from the acquired deficiency of cellular immunity caused by the human immunodeficiency virus (HIV). "‘...If you try to get closer to them they will say, “don’t get close to us, you will infect us with AIDS”’ (female, youth fgd1)." (PMID 23894625, 2013).
cutaneous melanoma (1 paper, 2021). A primary melanoma arising from atypical melanocytes in the skin. "Thus, this study was intended to investigate the roles of FGD1 and its underlying mechanisms in cutaneous melanoma." (PMID 34783295, 2021). "The data demonstrated that FGD1 was up-regulated and predicted a poor clinical outcome for cutaneous melanoma patients." (PMID 34783295, 2021). "Bioinformatics tools and quantitative real-time polymerase chain reaction (qRT-PCR) were used to analyze the expression of FGD1 in cutaneous melanoma." (PMID 34783295, 2021). "Similarly, the overexpression pattern of FGD1 was also found in cutaneous melanoma in our previous studies." (PMID 34783295, 2021). "FGD1 plays an important role in multiple cancers, but how it works in cutaneous melanoma has not been illustrated." (PMID 34783295, 2021).
fibrosarcoma (1 paper, 2020). A malignant mesenchymal fibroblastic neoplasm affecting the soft tissue and bone. "Similar to MDA-MB-231 cells, collagenolytic invadopodia enriched in cortactin, TKS5, and FGD1 were observed in association with the collagen fibers in HT-1080 fibrosarcoma cells." (PMID 32673397, 2020).
Hyperkalemia (1 paper, 2020). An abnormally increased potassium concentration in the blood. "The mineralocorticoid level in the patient with FGD1 was normal, while her hyponatremia might be due to vomiting, and the extent of hyperkalemia was extremely mild." (PMID 32903448, 2020).
hypogonadism (1 paper, 2020). A disorder characterized by decreased function of the gonads. "Given that, we are the first group to propose that FGD1 may be a potential dosage-sensitive gene responsible for the hypogonadism observed in our patients." (PMID 32381089, 2020).
Hyponatremia (1 paper, 2020). An abnormally decreased sodium concentration in the blood. "However, transient hyponatremia has been reported in several children with FGD1, sometimes leading to a misdiagnosis of AHC." (PMID 32903448, 2020).
microphthalmia (1 paper, 2023). Congenital or developmental anomaly in which the eyeballs are abnormally small. "A similar search of DR17 using the term microphthalmia resulted in 22 genes significant for the small eyes phenotype: Aldh1a3, Aff4, Bmp4, Cdk4, Cox6b1, Cxcr4, Dync1li1, Eef1d, Fgd1, Gne, Grh12, Mab21l2, Maf, Med13l, Mllt10, Mthfd2, Pex6, Phgdh, Ssr1, Stim1, Tdo2, and Vps26c." (PMID 36737727, 2023).
sarcoma (1 paper, 2020). A usually aggressive malignant neoplasm of the soft tissue or bone. "It has been found that the mRNA levels of FGD1 were up-regulated in 20 percent of sarcoma patients." (PMID 32194840, 2020).
X-linked disease (1 paper, 2019). X-linked form of disease. "Loss of function mutations in the FGD1 gene cause a rare X-linked disease, faciogenital dysplasia (FGDY, also known as Aarskog-Skott syndrome), which is associated with bone and urogenital abnormalities." (PMID 30778386, 2019).
tumor (6 papers, 2015 to 2025). "FGD1 is a guanine nucleotide exchange factor to control the activation of Rho GTPase, which is critical to normal development and tumor formation." (PMID 34783295, 2021). "Compared with the control group, the protein level of FGD1 tumor was significantly lower in FGD1-KD group." (PMID 34783295, 2021). "Here, we revealed that FGD1 participated in increasing PD-L1 expression and regulating the tumor immune response in a PTEN-dependent manner." (PMID 32194840, 2020). "FGD1 contributes to extracellular matrix formation 26, which is essential for tumor formation and bone development." (PMID 32194840, 2020). "In agreement with the previous findings, knockdown of FGD1 hindered the tumor growth and prolonged the survival time of the tumor-bearing mice." (PMID 32194840, 2020). "In the nude mice model, knockdown of FGD1 inhibited the growth of tumor tissue." (PMID 34783295, 2021). "Similarly, knockdown of FGD1 suppressed the tumor growth and decreased the number of Ki-67-positive cells, but overexpression of FGD1 reversed this process." (PMID 32194840, 2020). "The TKS5/FGD1 interaction, which was initially reported in a global human interactome study, is now validated by the present work in the context of stromal remodeling by tumor cells." (PMID 32673397, 2020). "Moreover, we observed that recusing the expression of FGD1 could reverse the decreased tumor cell proliferation effect induced by repression of FGD1 in MNNG/HOS cells." (PMID 32194840, 2020).
cancer (5 papers, 2012 to 2024). A tumor composed of atypical neoplastic, often pleomorphic cells that invade other tissues. "Collectively, our findings identified FGD1 as a novel interacting partner of TKS5 in matrix-degradative invadopodia in different cancer cell lines." (PMID 32673397, 2020). "All the exons of the FGD1 gene were analyzed for mutation, as mutations in this gene have never been reported in human cancers." (PMID 24137342, 2013).
infection (2 papers, 2020 to 2022). The state of being infected such as from the introduction of a foreign agent such as serum, vaccine, antigenic substance or organism. "FGD1 was repressed through infection with gene-specific short-hairpin RNA in U-2OS, MG63 and MNNG/HOS cells, respectively." (PMID 32194840, 2020).
FGD1 also shares sentences with these, for which no sentence is quoted: hepatocellular carcinoma (3 papers); prostate carcinoma (2); autosomal dominant mental retardation (1); bladder cancer (1); bone tumor (1); breast tumor (1); demyelinating disease (1); developmental delay (1); esophagus cancer (1); Hepatitis C) infection (1); hypothyroidism (1); lung adenocarcinoma (1); lupus (1); pancreatic cancer (1); sarcopenia (1).